SSMEM1 (serine rich single-pass membrane protein 1)
Description:
Essential for regulating the timely and localized migration of the Golgi apparatus during spermiogenesis, facilitating proper sperm head formation and motility, thus playing a crucial role in male fertility.
Synonyms: C7orf45; FLJ40316
Tractability: Antibody: UniProt predicts a signal peptide or a membrane-spanning region.
Gene: Protein-coding gene on chromosome 7 (130,206,344 to 130,216,844, forward strand). Ensembl gene ENSG00000165120.
Subcellular location: Membrane
Gene Ontology:
Molecular function: protein binding
Biological process: spermatogenesis
Cellular component: membrane
Genetic constraint (gnomAD): Loss-of-function variants: 14 observed, 12.36 expected, observed/expected ratio (o/e) 1.13, 90% interval 0.75 to 1.72. The upper end of that interval is the gene's LOEUF score, 1.72, which puts it in group 6 of 6, group 1 being the genes least tolerant of losing a copy. Missense variants: 259 observed, 307.72 expected, observed/expected ratio (o/e) 0.84, 90% interval 0.76 to 0.93. Synonymous variants: 96 observed, 104.24 expected, observed/expected ratio (o/e) 0.92, 90% interval 0.78 to 1.09.
Homologues: Orthologues: macaque SSMEM1 (94% identical), chimpanzee SSMEM1 (93% identical), dog SSMEM1 (77% identical), pig SSMEM1 (77% identical), rabbit SSMEM1 (71% identical), rat Ssmem1 (68% identical), mouse Ssmem1 (68% identical), guinea pig SSMEM1 (63% identical).
Diseases named in the same sentence as SSMEM1 in open-access papers:
SSMEM1 is named in the same sentence as 3 diseases in open-access papers, as found by Europe PMC text mining. Sharing a sentence is not in itself a finding about the gene and the disease. The quoted sentences say what the papers report.
Globozoospermia (1 paper, 2020). Any structural anomaly of the acrosome resulting in a round sperm head. "The sterility of the Ssmem1 KO (null) mice is associated with globozoospermia and loss of sperm motility." (PMID 32301969, 2020). "KO mice lacking Ssmem1, which is testis-specific and well-conserved in mammals, are sterile because of abnormal sperm head morphology (globozoospermia) and diminished motility." (PMID 32301969, 2020). "We observed that lack of Ssmem1 in male mice alters spermiogenesis, resulting in globozoospermia and sterility." (PMID 32301969, 2020). "Absence of serine-rich single-pass membrane protein 1 (SSMEM1) leads to male infertility because of globozoospermia in mice." (PMID 32301969, 2020).
Infertility (1 paper, 2020). "To further evaluate their infertility, we collected epididymal spermatozoa from adult Ssmem1 HET and KO males and examined the sperm motility using a Computer Assisted Sperm Analysis (CASA) system." (PMID 32301969, 2020).
SSMEM1 also shares sentences with these, for which no sentence is quoted: male infertility (1 paper).